MMP3 (matrix metallopeptidase 3)
Diseases named in the same sentence as MMP3 in open-access papers (continued):
Sharing a sentence is not in itself a finding about the gene and the disease.
spinal stenosis (1 paper, 2009). Narrowing of the spinal canal. "The expression of active MMP-3 was slightly higher in the spinal stenosis samples than that in the disc herniation samples, but the difference was not statistically significant (p = 0.131)." (PMID 19885059, 2009). "The MMP-3 expression was slightly higher in the patients with spinal stenosis than that in the disc herniation patients, but the difference was not statistically significant (p = 0.131)." (PMID 19885059, 2009). "Although the mean density (arbitrary units) of active MMP-3 was slightly higher in the spinal stenosis specimens than that in the disc herniation specimens, the difference was not statistically significant (329.24 ± 65.91 vs. 305.24 ± 71.35, respectively, p = 0.131)." (PMID 19885059, 2009). "Western blot analysis demonstrated the expressions of active MMP-2, MMP-3, and MMP-13 in the ligamentum flavum specimens of the spinal stenosis patients and the disc herniation patients." (PMID 19885059, 2009). "Immunohistochemical analysis demonstrated that MMP-2, MMP-3, and MMP-13 were positively stained on the ligamentum flavum fibroblasts of the patients with spinal stenosis and disc herniation, respectively." (PMID 19885059, 2009).
stable angina (1 paper, 2021). "MMP‐3 and ‐9 have higher plasma levels in patient subgroups than in the control group, the highest MMP‐3 and‐9 levels were obtained in the most severe presentation of CAD (STEMI) compared to NSTEMI and stable angina patients (P < 0.0001, for both)." (PMID 33381894, 2021).
status epilepticus (1 paper, 2021). Status epilepticus is defined as a continuous seizure lasting more than 30 min, or two or more seizures without full recovery of consciousness between any of them. "Following status epilepticus, transcripts of matrix metalloproteinases such as MMP3, ADAMTS5, ADAMTS8, and ADAMTS9 were induced." (PMID 35185464, 2021).
synovial sarcoma (1 paper, 2016). "The aim of this study was to elucidate the mechanisms underlying IL-17A-induced MMP-3 expression in the human synovial sarcoma cells HS-SY-II." (PMID 26850593, 2016). "Our results indicate an essential role for MAPKs in the induction of MMP-3 in synovial sarcoma cells, through AP-1 activation." (PMID 26850593, 2016). "In the present study, we have explored the role of IL-17A in the MMP-3 expression of synovial sarcoma cell lines, HS-SY-II." (PMID 26850593, 2016). "Our preliminary findings provide a valuable insight how IL-17A may contribute to the pathogenesis of synovial sarcoma by stimulating MMP-3 expression." (PMID 26850593, 2016). "In the present study, we examined the molecular mechanism by which IL-17A-induced MMP-3 expression in synovial sarcoma cells and demonstrated that IL-17 could regulate the expression of MMP-3 through MAPKs-AP-1 activation." (PMID 26850593, 2016).
thoracic aortic aneurysm (1 paper, 2009). An aneurysm formed in the wall of the proximal portion of the descending aorta proceeding from the arch of the aorta. "Mean values of MMP-3 were lower in the control group (group E) and higher in patients with thoracic aortic aneurysm (group C)." (PMID 19886986, 2009).
Thrombocytopenia (1 paper, 2024). A reduction in the number of circulating thrombocytes. "Thrombocytopenia led to a significant reduction in intratumor PAI-1, MMP-3, MMP-9, and MPO, specifically in B16F1 tumors." (PMID 38493157, 2024).
thyroid (1 paper, 2024). "We hypothesized that MMP-3 might be more related to thyroid disease than ophthalmopathy." (PMID 39259164, 2024).
tongue squamous cell carcinoma (1 paper, 2023). A squamous cell carcinoma that arises from the tongue. "The expression of MMP3 and ILF3 was up-regulated in tongue squamous cell carcinoma." (PMID 36941602, 2023).
urolithiasis (1 paper, 2023). Stone(s) within the urinary tract. "For LASSO regression analysis, six variables, MMP1, MMP3, MMP9, MMP10, MMP27 and, MMP28, were screened as diagnostic markers for urolithiasis." (PMID 37006258, 2023). "Subsequently, we extracted DMMMPs and genes in urolithiasis-related modules for intersection and found MMP1, MMP3, MMP9, MMP12 were in the royalblue module and MMP10 were in the green module, suggesting all of DEMMPs might be implicated in RPs and urolithiasis." (PMID 37006258, 2023).
tumor (457 papers, 1999 to 2026). "Interleukin-7 (IL-7), acting via the IL-7 receptor (IL-7R), plays a significant role in tumor progression, is closely associated with a poor prognosis for patients with PC, and is associated with MMP-3 and MMP-7 expression." (PMID 40001606, 2025). "MMP3 has been shown to promote mammary tumorigenesis and has been proposed as a biomarker of cancer risk and tumour progression in patients with breast cancer." (PMID 38926506, 2024). "MMP3 is over-expressed in various human tumor tissues, and is considered a potential diagnostic or prognostic biomarker of some cancers." (PMID 38675723, 2024). "We propose that MMP3 is a marker for tumor-associated fibroblasts and a specific biomarker for HSCC." (PMID 38720887, 2024). "In our study, we discovered a unique CAF cluster in HSCC, CAF_C2_MME, originating from tumor samples, with MMP3 as its associated gene, predominantly expressed in fibroblasts and significantly overexpressed in HSCC tissues." (PMID 38720887, 2024). "MMP-3, from the stromelysin class, is also associated with tumor progression and activates MMP-9 trough partial proteolysis." (PMID 38003553, 2023). "Both IgG1 and IgG4 are cleaved within the lower hinge by a number of inflammatory and/or tumor associated proteases -MMP-3 and MMP-12 at one site, Cathespin at a second site and by MMP-7/pepsin at a third site." (PMID 37713423, 2023). "CAF-derived MMP3, secreted by tumor-associated myo-fibroblasts, is sufficient to promote AGS cell migration." (PMID 35269560, 2022). "Meanwhile, this P15 aptamer was associated with reduced matrix metallopeptidase 3 (MMP3) expression highly related to tumor cell invasion." (PMID 35652096, 2022). "Aberrant abundance of MMP3 is a general event which has been observed in multiple tumors, and high abundance of MMP3 is also associated with malignant phenotype of tumor cells such as invasion and migration." (PMID 36033831, 2022). "We thus found that that (i) MMP3-high, LuM1-derived EVs augmented the tumor growth in vitro and (ii) the loss of MMP3 in EVs diminished the protumorigenic properties of the EVs." (PMID 32429403, 2020). "Different microglial-derived factors including proteases (e.g., Ctss, Mmp3, and Mmp9), Wnt signaling components or chemokines (e.g., Cxcl12) have been implicated in assisting tumor cells to cross the BBB and colonize the brain parenchyma." (PMID 33384994, 2020). "Given that MMP-3 is associated with tumor-activated stromal cells, a novel MMP-3-sensitive NIRF probe has been designed in our laboratory to detect stromal cell activation by early-stage EOC." (PMID 29390034, 2018). "The increased expression of MMP3 was found to cause a slight increase at the protein level in the SG-/- tumour tissue." (PMID 27223472, 2016). "Although MMP3 expression was originally linked to tumor initiation, the role of MMP3 beyond this stage has remained unclear." (PMID 26008967, 2015). "Elevated expression of MMP-3, Pthlh and S100a8 was confirmed in isolated primary tumour epithelial cells of the two metastatic variants, as was expression of S100a9, a binding partner for S100a8." (PMID 25633981, 2015). "The relevance of this IRF8-MMP3 axis in tumor growth in vivo was exemplified by the finding that knockdown of MMP3 expression significantly abrogated the enhanced tumor growth effect caused by IRF8-loss." (PMID 26008967, 2015). "Although MMP3 levels have been originally linked to tumor initiation/promotion, less is known about their role in subsequent stages of the neoplastic process." (PMID 26008967, 2015). "The causal link between tumor-derived MMP3 expression and malignant behavior was also demonstrated using MMP3 gain- or loss-of-function approaches." (PMID 26008967, 2015). "While only MMP1 was associated with tumor differentiation, MMP3 and MMP9 were associated with ER−/PR− tumors." (PMID 23696797, 2013).
tumor (continued). "Overexpression of MMP-1, MMP-2, and MMP-3 has been linked to poor prognosis, high tumour stage, and enhanced tumour invasiveness in patients with CRC." (PMID 17311017, 2007). "The MMP2 and MMP3 transcriptionally more active polymorphisms appear more frequently among individuals with many moles, tumor infiltrating lymphocytes, and low Clark level, and the number of alleles seems associated with absence of ulceration." (PMID 17958893, 2007). "Their results indicate that the 5A polymorphism in the MMP-3 promoter may contribute to tumor formation and advancement." (PMID 40564842, 2025). "For example, post-transcriptional regulation, tumor microenvironment cues, or linkage disequilibrium with other functional variants could contribute to elevated MMP-3 levels despite the presence of the lower-activity 6A allele." (PMID 40564842, 2025). "Importantly, MMP3 expression is significantly higher in human TNBC with KMT2C mutations compared with WT tumours, and MMP3-high tumours have significantly higher frequencies of KMT2C mutation." (PMID 38926506, 2024). "For relationship between MMP polymorphism and tumor prognosis, two genetic variants of MMP-3 could drastically increased risk of tumor progression and distant metastasis." (PMID 37188722, 2023). "In addition, a variety of cytokines, including TNF-alpha (TNF-α), TGF-beta (TGF-β), MMP2 (matrix metalloproteinase-2), and MMP3, are associated with the proliferation, invasion and metastasis of tumor cells." (PMID 37895145, 2023). "High levels of MMP3 are associated with stronger tumor aggressiveness and poor prognosis." (PMID 37497415, 2023). "Furthermore, WFEA significantly increased the protein expression of apoptosis-related Caspase3, inhibited the protein expression levels of MMP3 (associated with tumor invasion and metastasis) and apoptosis-inhibiting gene Bcl2." (PMID 36949111, 2023). "These included amplification of a cluster of MMPs on chromosome 11q22.3, including MMP1 and MMP3, which have been previously associated with tumour-induced muscle loss in drosophila models 32, as well as amplifications involving ADIPOQ (Adiponectin) on chromosome 3q27.1." (PMID 37045997, 2023). "In addition, adipocytes can increase the invasive ability of tumor cells to the body and increase the metastatic risk of lung tumors by producing exosomes with high levels of MMP3." (PMID 35227278, 2022). "MMP3, encoding a kind of protein as a member of matrix metalloproteinase, was well known to be involved in tumor progression and invasion, while specific peptide inhibitors targeting MMP3 could suppress HCC cell migration." (PMID 36714595, 2022). "Moreover, transcript levels of genes associated with CRC susceptibility loci (e.g., Grem1 and Bmp4) and tumor development and invasion (e.g., Wnt5a, Ereg, Mmp3, Mmp13, Timp1, Saa3, Ptgs2, and Acsl4) were elevated in IL-11+ fibroblasts." (PMID 33863879, 2021). "Nevertheless, the loss of MMP3 was crucial to reduce tumor and EV development." (PMID 32429403, 2020). "Moreover, we observed that MMP3 enzymatic activities were significantly associated with metastasis of tumor." (PMID 32922541, 2020). "We next examined whether the serum levels of MMP-3 contributed by both stromal and tumor cells were associated with disease progression." (PMID 28831065, 2017). "MMP-3, S100a8, S100a9 and Pthlh transcripts were all upregulated significantly in isolated primary tumour cells of the metastatic variants in both pairs, reflecting the deregulation observed in whole tumours." (PMID 25633981, 2015). "Only MMP3 was significantly associated with more advanced tumor stage." (PMID 23696797, 2013). "In addition, tumor fibroblasts with the 5A/5A genotype were associated with significantly higher levels of MMP-3 release than normal fibroblasts with the 5A/5A genotype (p = 0.028) and this correlated also with a high IPC phenotype." (PMID 17922906, 2007).
tumor (continued). "This study has shown that tumor-fibroblast-derived MMP-3 release, associated with the MMP-3 5A/5A genotype, enhances tumor invasion, and it suggests that women with this genotype may suffer from enhanced tumor progression." (PMID 17922906, 2007). "Notably, MMP3 has been implicated in stimulating tumor cell metastasis in OS." (PMID 39431237, 2024). "We therefore hypothesized that the molecular transmission of MMP3 during tumor–stroma interaction could underlie the pro-tumorigenic and pro-metastatic roles of this multi-functional proteinase, and we also aimed to investigate this mechanism in the present study." (PMID 32260433, 2020). "In addition, MMP-3 activity may reflect a wound-healing response of the associated tumor stroma as MMP-3 attempts to reconcile the tumor cells back into a normal tissue structure and to limit cancer cell invasion." (PMID 29390034, 2018). "Based on earlier findings that IRF8-loss augmented tumor growth and that this malignant phenotype was inversely associated with an unexpected increase in MMP3 expression (by microarrary analysis), we hypothesized that MMP3 is downregulated by a novel IRF8-dependent mechanism." (PMID 26008967, 2015). "Integrated genomic analysis of microarray data from primary tumours of the two different isogenic pairs revealed that MMP-3, Pthlh and S100a8 were commonly upregulated and that Cd36 was commonly downregulated, indicating that these genes might be causal in tumour cell dissemination." (PMID 25633981, 2015). "UBD overexpression promotes tumor growth, while MMP3 knockdown inhibits both tumor growth and metastasis." (PMID 41583390, 2026). "MMP-3 belongs to the group of stromelysins, and its important role in tumour cell differentiation and proliferation, as well as in angiogenesis has been demonstrated." (PMID 40565125, 2025). "The immunoreactivity of MMP-1 and MMP-3 in tumor cells was significantly higher than in normal tissues." (PMID 40564842, 2025). "We investigated the biological effects of MMP3-siRNA therapy on tumor cell proliferation and blood vessel formation." (PMID 40362252, 2025). "Cisplatin exposure leads to MMP3 promoter demethylation, enhancing chemoresistance, tumor growth, and metastasis." (PMID 40362252, 2025). "The MMP-3 was found to be more expressed in healthy stroma compared to tumor stroma, and MMP-2 was more expressed in T cell tumors compared to B cell tumors, a similar result to BDNF." (PMID 40427122, 2025). "It induced immunogenic cell death (ICD) characterized by calreticulin exposure and ATP release, while modulating the tumor microenvironment by downregulating MMP-3, MMP-9, VEGF, and vimentin, and restoring epithelial markers." (PMID 41304785, 2025). "Nevertheless, the secretion of other molecules implicated in the regulation of tumor angiogenesis in CM (e.g., MMP-2, MMP-3, MMP-8) were significantly reduced in Spry1KO Mel 593 clones." (PMID 39953610, 2025). "Upregulation of Mmp3 and Mmp9 genes directly reflects tumor cells’ ability to breach physical barriers and acquire invasive capabilities." (PMID 41415031, 2025). "In vivo, MMP3-siRNA therapy alone did not significantly reduce tumor size; however, when combined with cisplatin, it resulted in a marked decrease in tumor growth, proliferation, and angiogenesis, reinforcing MMP3’s role in mediating chemoresistance." (PMID 40362252, 2025). "A comprehensive pan-cancer analysis of MMP gene expression profiles across various neoplasms revealed that MMP-3 is significantly up-regulated in at least 10 cancer types; however, it did not identify any notable findings related to MMP-3 in MPNs." (PMID 40724896, 2025). "A unique cluster of tumor cells in D‐TGCT is identified that regulated differentiation of CD34+ fibroblasts into MMP3+ fibroblasts or APOE+ fibroblasts via COL6A3 − (ITGAV + ITGB8) interaction." (PMID 40126353, 2025).
tumor (continued). "For example, MMP3 has been found to enhance the pro-tumorigenic activities of CAFs, leading to increased tumor cell invasion and metastasis." (PMID 40362252, 2025). "Overall, our results indicate that increased MMP3 levels contribute to cisplatin resistance in OC, highlighting the need to further investigate the mechanisms of MMP3 regulation in tumor cells and their microenvironment." (PMID 40362252, 2025). "MMP3 is a member of the matrix metalloproteinases family, which promotes the migration, invasion and metastasis of cancer cells by altering tumor environment, intracellular signaling pathways, and transcription." (PMID 41425852, 2025). "Emerging research has consistently demonstrated that MMP3 plays a pivotal role as a regulatory factor within a set of biological pathways to inhibit the tumor metastasis." (PMID 40575254, 2025). "We recently reported that MMP3 is post-transcriptionally regulated by miR-18a, a microRNA with a tumor-suppressive role in cisplatin-resistant OC cells." (PMID 40362252, 2025). "It is well-documented that MMP3 levels increase in various types of cancer which facilitates tumor cell invasion and metastasis." (PMID 41450565, 2025). "The matrix metalloproteinase (MMP) family, including MMP3, influences tumorigenesis by impacting fibroblasts and degrading the extracellular matrix, potentially facilitating tumor cell invasion and migration." (PMID 38720887, 2024). "Mmp1a, Mmp3, and Mmp13, which engage in metastasis through facilitating invasion of tumor cells, were downregulated in Setd7 KO and CPH groups compared to Setd7 WT group." (PMID 39522095, 2024). "Both MMP3 and MMP 9 play a pivotal role in the degradation of the extracellular matrix causing tumor invasion, metastasis and vascularization of tumor tissue." (PMID 38473807, 2024). "On one hand, MMP-3 exerts tumor-suppressive effects by catalyzing the production of factors that inhibit angiogenesis through the degradation of plasminogen and type VIII collagen." (PMID 39769318, 2024). "eHSP90β-dependent binding to the MMP3 hemopexin domain for MMP3 activation for TME remodeling. eHSP90β downregulation leads to tumor dormancy." (PMID 38994941, 2024). "Taken together, these results show that indirect inhibition of MMP3 via targeting KDM6A prevents metastasis of KMT2C or KMT2D mutant tumours." (PMID 38926506, 2024). "These tumor suppressors inhibit cell proliferation by targeting matrix metallopeptidase 3, inhibit metastasis, and induce apoptosis." (PMID 38245882, 2024). "Extracellular vesicles play a pivotal role in facilitating the molecular transfer of MMP3, thereby augmenting tumor proliferation and onset." (PMID 39431237, 2024). "Based on using immortalized epithelial cell lines or transgenic mouse models, MMP3 plays an important role in tumor initiation." (PMID 39177661, 2024). "Single-cell RNA-sequencing of cell populations from the NIH dbGaP in the PDAC TME indicates that MMP3 is expressed in the tumor and MMP11 is expressed in the stromal populations." (PMID 38619621, 2024). "Similar results were observed in the 4T1-bearing BALB/c mouse model, where HFD feeding significantly increased ECM1 protein levels in the sEVs, as well as ECM1, MMP3, and S100A/B protein levels in the tumor tissues." (PMID 38402239, 2024). "MMP-3 promotes spontaneous tumour formation in mice, and subsequent analysis of this process revealed that the exposure of cultured mammary epithelial cells to MMP-3 directly activated EMT." (PMID 38956273, 2024). "D-sEVs treatment also significantly enhances ECM1-mediated BC metastasis and growth in mouse models, as evidenced by the elevated tumor levels of MMP3 and S100A/B." (PMID 38402239, 2024). "Previously, substantial expression of MMP-1 and MMP-3 was observed in OSCC cases involving poor prognosis and metastasis, and this is associated with tumor progression and poor survival rates." (PMID 36839884, 2023).